LY96 (lymphocyte antigen 96)
Description:
Binds bacterial lipopolysaccharide (LPS). Cooperates with TLR4 in the innate immune response to bacterial lipopolysaccharide (LPS), and with TLR2 in the response to cell wall components from Gram-positive and Gram-negative bacteria. Enhances TLR4-dependent activation of NF-kappa-B. Cells expressing both LY96 and TLR4, but not TLR4 alone, respond to LPS.
Synonyms: Ly-96; MD2; MD-2; ESOP-1
Tractability: Small molecule: a drug acting on it is in phase 2 or 3 trials; a structure with a bound ligand is known; a high-quality ligand is known; it has a high-quality binding pocket. Antibody: UniProt places it where antibodies can reach, with high confidence; its Gene Ontology location is reachable by antibodies, with high confidence; UniProt predicts a signal peptide or a membrane-spanning region. PROTAC: its protein half-life has been measured; a small molecule that binds it is known.
Target class: Surface antigen
Gene: Protein-coding gene on chromosome 8 (73,991,392 to 74,029,079, forward strand). Ensembl gene ENSG00000154589.
Subcellular location: Secreted, extracellular space; Secreted
Subcellular location (Human Protein Atlas): Vesicles; Predicted to be secreted
Pathways (Reactome):
Immune System: Activation of IRF3, IRF7 mediated by TBK1, IKKε (IKBKE); ER-Phagosome pathway; IKK complex recruitment mediated by RIP1; IRAK2 mediated activation of TAK1 complex upon TLR7/8 or 9 stimulation; MyD88-independent TLR4 cascade; MyD88:MAL(TIRAP) cascade initiated on plasma membrane; Regulation of TBK1, IKKε (IKBKE)-mediated activation of IRF3, IRF7; Regulation of TLR by endogenous ligand; TRAF6-mediated induction of TAK1 complex within TLR4 complex; TRIF-mediated programmed cell death; Toll Like Receptor 4 (TLR4) Cascade
Disease: Dengue Virus-Host Interactions; IRAK4 deficiency (TLR2/4); MyD88 deficiency (TLR2/4); RSV-host interactions; Respiratory syncytial virus (RSV) attachment and entry
Cellular responses to stimuli: Heme signaling
Programmed Cell Death: Caspase activation via Death Receptors in the presence of ligand
Gene Ontology:
Molecular function: lipopolysaccharide immune receptor activity; protein binding; coreceptor activity; lipopolysaccharide binding; Toll-like receptor 4 binding
Biological process: detection of lipopolysaccharide; response to lipopolysaccharide; toll-like receptor signaling pathway; cell surface receptor signaling pathway; cellular defense response; cellular response to lipopolysaccharide; innate immune response; positive regulation of lipopolysaccharide-mediated signaling pathway; positive regulation of tumor necrosis factor production; toll-like receptor 4 signaling pathway; lipopolysaccharide-mediated signaling pathway; pattern recognition receptor signaling pathway
Cellular component: extracellular region; lipopolysaccharide receptor complex; plasma membrane; receptor complex; endosome membrane
Genetic constraint (gnomAD): Loss-of-function variants: 5 observed, 3.14 expected, observed/expected ratio (o/e) 1.59, 90% interval 0.73 to 1.94. That is too few expected variants to judge how well the gene tolerates losing a copy. Missense variants: 28 observed, 32.45 expected, observed/expected ratio (o/e) 0.86, 90% interval 0.64 to 1.18. Synonymous variants: 8 observed, 11.32 expected, observed/expected ratio (o/e) 0.71, 90% interval 0.41 to 1.27.
Homologues: Orthologues: chimpanzee LY96 (99% identical), macaque LY96 (93% identical), dog LY96 (72% identical), guinea pig LY96 (65% identical), mouse Ly96 (62% identical), pig LY96 (62% identical), rat Ly96 (54% identical).
Diseases named in the same sentence as LY96 in open-access papers:
LY96 is named in the same sentence as 182 diseases in open-access papers, as found by Europe PMC text mining. Sharing a sentence is not in itself a finding about the gene and the disease. The quoted sentences say what the papers report.
Sepsis (46 papers, 2009 to 2025). Sepsis is defined as life-threatening organ dysfunction caused by a dysregulated host response to infection. "The results showed significantly higher levels of OLAH, HPGD, and LY96 in sepsis patients compared to those with preoperative conditions or pneumonia, increased by 95.16-, 6.58-, and 2.89-fold, respectively, while ABLIM1 was downregulated by 7.33-fold." (PMID 39628572, 2024). "The refined model, comprising genes OLAH, LY96, HPGD, and ABLIM1, demonstrated high predictive accuracy for 28-day mortality and excelled in early sepsis detection." (PMID 39628572, 2024).
colon cancer (10 papers, 2014 to 2025). "LY96, which is known as MD-2, targeting it therapies have been shown to prevent colon cancer growth and lung metastasis." (PMID 36189275, 2022). "The interaction of LY96 and TLR4 promotes the release of pro-inflammatory cytokines and adhesive molecules, which accelerates colon cancer growth and lung metastasis." (PMID 37662929, 2023). "LY96 interacted with TLR4 and activated the nuclear factor-κB (NF-κB) pathway, and thereby promoted the production of pro-inflammatory cytokines and adhesive molecules in colon cancer cells, which accelerate colon cancer growth and lung metastasis." (PMID 35647025, 2022).
atherosclerosis (9 papers, 2020 to 2025). A disease characterized by the build-up of fatty material and calcium deposition in the arterial wall resulting in partial or complete occlusion of the arterial lumen. "Through analysis of the public database, seven hub genes (UQCR11, UBE2N, ADD1, TLN1, IRAK3, LY96, and MAP3K1) have recently been found to be strongly associated with familial hypercholesterolemia and contribute to a higher risk of atherosclerosis." (PMID 34895070, 2021). "Our study identified seven core genes (UQCR11, UBE2N, ADD1, TLN1, IRAK3, LY96, and MAP3K1) that are strongly linked to FH and lead to a higher risk of atherosclerosis." (PMID 32760426, 2020). "In the atherosclerosis dataset GSE28829, CD14 (AUC = 0.938), C1QB (AUC = 0.947), CD53 (AUC = 0.952), LY96 (AUC = 0.904), P2RX7 (AUC = 0.981), C3 (AUC = 0.817), and TNFSF13B (AUC = 0.875) demonstrated favorable diagnostic efficiency for differentiating patients with atherosclerosis from controls." (PMID 37649719, 2023).
breast carcinoma (8 papers, 1989 to 2023). "However, LY96 was downregulated in breast cancer, and LY96 suppression can inhibit cancer development both in vivo and in vitro, which was inconsistent with our result." (PMID 35647025, 2022). "Next, we wanted to decipher whether the positive correlation between SFRP1 and BDNF expression on the one hand and the negative correlation between SFRP1 and LY96 expression on the other hand is also detectable in human breast cancer." (PMID 25036590, 2014).
fibrosis (6 papers, 2017 to 2025). the formation of excess fibrous connective tissue in an organ or tissue in a reparative or reactive process. "Fibrosis and HCC: Our RNAseq analysis of the livers from Efcab4b−/− mice exhibit downregulation of the macrophage marker CD163, the CD44 antigen and Lymphocyte antigen 96 (Ly96) and upregulation of beta-1, 4-galactosyltransferase 1 (B4GALT1)." (PMID 40034259, 2025).
ischemic stroke (6 papers, 2010 to 2026). A stroke disorder caused by obstruction of blood flow to the brain, due to thrombotic (local blood clot formation) or embolic (due to a blood clot or other material traveling from another site) event. "However, many genes associated with ischemic stroke are not affected by tPA including BCL6, F5, and LY96 which were previously found to be predictive of ischemic stroke in humans." (PMID 20406488, 2010).
Stroke (6 papers, 2015 to 2026). Sudden impairment of blood flow to a part of the brain due to occlusion or rupture of an artery to the brain. "Human stroke genomic biomarker studies have identified a common panel of five genes responding to AIS in the peripheral blood: arginase 1 (ARG1), lymphocyte antigen 96 (LY96), matrix metalloproteinase 9 (MMP9), s100 calcium-binding protein A12 (s100A12), and chemokine CC motif receptor 7 (CCR7)." (PMID 26515089, 2016).
rheumatoid arthritis (5 papers, 2015 to 2024). A chronic, systemic autoimmune disorder characterized by inflammation in the synovial membranes and articular surfaces. "LY96 is considered to play a key role in inflammation and immune-related diseases such as rheumatoid arthritis, Crohn’s disease, and inflammatory diabetic cardiomyopathy." (PMID 37662929, 2023). "LY96, also known as MD2, encodes a protein which often is a coreceptor with TLR4 forming the TLR4/MD2 complex and has previously been found to be upregulated in patients with rheumatoid arthritis." (PMID 34177888, 2021). "For rheumatoid arthritis, systemic lupus erythematosus, ankylosing spondylitis and osteoarthritis diseases, those common factors include TNFSF10, CX3CR1, LY96, TLR5, TXN, TIA1, PRKCH, and PRF1." (PMID 26352601, 2015).
Hyperglycemia (4 papers, 2018 to 2020). An increased concentration of glucose in the blood. "Our microarray experiments demonstrated that metformin upregulated downstream targets in VEGFA pathway; MMP16, FABP4, ROCK1, TFPI2, CXCL-8, and LY96 under hyperglycemia-CoCl2, which play a part in cell migration." (PMID 29351188, 2018).
periodontitis (4 papers, 2015 to 2024). An acute or chronic inflammatory process that affects the tissues that surround and support the teeth. "Five hub ICD-related genes (ENTPD1, TLR4, LY96, PRF1 and P2RX7) were identified for the construction of a diagnostic model for periodontitis." (PMID 39555084, 2024). "Results of our study discovered that the most significant crosstalk genes between periodontitis and MS were FAM46C, SLC7A7, LY96, CFI, DDIT4L, CD14, and IGJ, which may be associated with response to molecules of bacterial origin." (PMID 38218802, 2024). "Five key genes associated with ICD (ENTPD1, TLR4, LY96, PRF1 and P2RX7) may be diagnostic biomarkers of periodontitis and future therapeutic targets." (PMID 39555084, 2024). "Periodontitis patients have significantly elevated levels of LY96, which leads to the formation of LY96-TLR4-CD14 complexes that trigger the myeloid differentiation factor-88 (MyD88) pathway, resulting in TNF-α, IL-6, IL-8, and IL-2 production in the gingival tissue." (PMID 39555084, 2024). "Venn diagrams revealed that there were eight shared genes (FAM46C, SLC7A7, LY96, CFI, DDIT4L, CD14, C5AR1, and IGJ) that overlapped between periodontitis and MS which were screened by WGCNA and DEGs." (PMID 38218802, 2024). "In line with the findings of the validation set, our findings demonstrated that ENTPD1, TLR4, LY96, PRF1 were elevated in periodontitis patients while P2RX7 expression was decreased." (PMID 39555084, 2024). "In contrast to the healthy group, the periodontitis group had higher levels of ENTPD1, TLR4, LY96, and PRF1 expression and lower levels of P2RX7 expression, according to the qPCR data." (PMID 39555084, 2024).
COVID-19 (3 papers, 2022 to 2025). A disease caused by infection with severe acute respiratory syndrome coronavirus 2. "The gene expression of S100A9, GAPDH, and LY96 was increased in all data of severe COVID-19 patients." (PMID 38262689, 2024). "Our analysis revealed that severe COVID-19 patients exhibit overexpression of genes coding for proteins of extracellular exosomes, endomembrane system, and neutrophil granules (e.g., S100A9, LY96, and RAB1B), which may play an essential role in the cellular response to infection." (PMID 38262689, 2024).
liver fibrosis (3 papers, 2018 to 2025). "In a mouse model of NASH, knockout of Ly96 significantly attenuated triglyceride accumulation, lipid peroxidation, inflammation and liver fibrosis." (PMID 40034259, 2025).
psoriasis (3 papers, 2021 to 2025). An autoimmune condition characterized by red, well-delineated plaques with silvery scales that are usually on the extensor surfaces and scalp. "Furthermore, genetic polymorphisms of TLRs, IL-1β, LY96, and TIRAP have been associated with a response to anti-TNFα or ustekinumab in psoriasis." (PMID 37511413, 2023).
rheumatic diseases (3 papers, 2015 to 2025). "Possibly reflecting the role of Ly96 (also known as MD-2) modulates immune pathways in rheumatic diseases and as a co-receptor in Toll-like receptor signaling." (PMID 40843700, 2025). "We identified a total of eight differentially expressed genes (TNFSF10, CX3CR1, LY96, TLR5, TXN, TIA1, PRKCH, PRF1), each associated with at least 3 of the 4 studied rheumatic diseases." (PMID 26352601, 2015). "By jointly analyzing 6 published microarray gene expression datasets about RA, SLE, OA and AS, we identified eight genes (TNFSF10, CX3CR1, LY96, TLR5, TXN, TIA1, PRKCH, PRF1) presenting general importance to rheumatic diseases." (PMID 26352601, 2015).
systemic lupus erythematosus (3 papers, 2015 to 2025). An autoimmune multi-organ disease typically associated with vasculopathy and autoantibody production. "Some researchers believe that VaD may be linked to systemic autoimmune diseases, and through bioinformatics and ML methods, genes such as C1QA, CD163, LY96, and MS4A4A have been identified as potential biomarkers for the link between VaD and systemic lupus erythematosus." (PMID 39116438, 2024).
thyroid cancer (3 papers, 2022 to 2025). "For instance, LY96 and IFNGR1 were identified as prognostic genes in thyroid cancer (THCA); LY96 is strongly downregulated in osteosarcoma, where it suppresses cell proliferation, migration, and invasion; and IFNGR1 has been associated with poor prognosis in metastatic prostate cancer." (PMID 41150760, 2025).
Arthritis (2 papers, 2024). Inflammation of a joint. "Consequently, RPL22L1 and LY96 may help regulate immune cells and contribute to the development of arthritis." (PMID 39509434, 2024).
hepatocellular carcinoma (2 papers, 2022 to 2023). A malignant tumor that arises from hepatocytes. "Additionally, TLR4 and LY96, which are genes in the TLR signaling pathway that promote cell survival and proliferation in hepatocellular carcinoma, were significantly downregulated in shTREM1 HepG2 tumors." (PMID 37651197, 2023).
Amoebiasis (1 paper, 2019). "In addition, the up-regulated DEGs were significantly enriched in 12 pathways such as NF-kappa B signaling pathway including LYN, LY96, CCL4, CD14; ECM-receptor interaction pathway including CD44, COL6A3, COL1A2, FN1 and Amoebiasis pathway including COL1A2, ITGB2, CD14, FN1." (PMID 31355054, 2019).
dementia (1 paper, 2009). Loss of intellectual abilities interfering with an individual's social and occupational functions. "DAP12/TYROBP and LY96 were among the genes whose expression was significantly affected in successful aging and in dementia in oldest-old persons, albeit in different directions." (PMID 19865478, 2009).
E. coli infection (1 paper, 2009). "The expression of TLR4, CD14 and MD-2 (encoding MD-2 protein; alternatively known as LY96 encoding Lymphocyte antigen 96 protein) was examined next because E. coli infection is particularly important after parturition and paves the way for other pathogens to cause uterine disease." (PMID 19476661, 2009).
endometriosis (1 paper, 2022). The growth of functional endometrial tissue in anatomic sites outside the uterine body. "According to western blot analysis, the protein levels of LY96, PDLIM3, and PTGIS were higher in the tissues of endometriosis patients." (PMID 36339397, 2022). "Quantitative assessments of histological images clearly demonstrated higher expression levels of LY96, PDLIM3, PTGIS, and WISP2, proteins in tissues from patients with endometriosis, in line with integrative analysis results." (PMID 36339397, 2022).
kidney cancer (1 paper, 2022). Primary or metastatic malignant neoplasm involving the kidney. "Our results showed that the deletion of risk genes, such as TLR3 and LY96, were lethal for kidney cancer cells." (PMID 36189275, 2022).
lung carcinoma (1 paper, 2013). "Of the 12 common Significant DNA methylated genes common to Stages I and II, LY96 has been previously associated with lung cancer; ZNF577 and LVRN have been identified as methylated in lung cancer and renal carcinoma, but not in LUAD." (PMID 24369052, 2013).
Miscarriage (1 paper, 2025). A pregnancy that ends at a stage in which the fetus is incapable of surviving on its own, defined as the spontaneous loss of a fetus before the 22th week of pregnancy. "Three significant genes – FOS, FOSB, and LY96 – associated with miscarriage were identified; these genes are up-regulated during infection but suppressed by the vaccine." (PMID 41232126, 2025). "Further research on 17 core enriched genes expressed at the MFI indicated that CXCL11, MMP10, FOS, FOSB, LY96, and NCF2 may be closely related to miscarriage." (PMID 41232126, 2025).
myopia (1 paper, 2025). "A study found that lymphocyte antigen 96 (LY-96) mRNA expression was increased in myopia and LY96 was negatively associated with the “Aminoacyl-tRNA biosynthesis” pathway." (PMID 41224847, 2025).
renal cell carcinoma (1 paper, 2022). "LY96 is essential to the proliferation of kidney inflammation in chronic renal disease and closely related to proliferation of renal cell carcinoma with a poor prognosis." (PMID 35630098, 2022).
schizophrenia (1 paper, 2025). A major psychotic disorder characterized by abnormalities in the perception or expression of reality. "In our study, a ceRNA network was constructed through LY96 and TMEM123, indicating that this regulatory network plays a role in schizophrenia, which provides direction and evidence for further elucidating the mechanisms of these biomarkers in SCZ." (PMID 40242178, 2025). "Our study reveals that LY96 expression is significantly elevated in schizophrenia patients compared to control samples, thereby supporting the involvement of LY96 in LPS-induced TLR4 signaling pathway activation and the pathogenesis of schizophrenia." (PMID 40242178, 2025).
infection (48 papers, 2005 to 2026). The state of being infected such as from the introduction of a foreign agent such as serum, vaccine, antigenic substance or organism. "Allelic variants of the genes MYD88 and LY96 associated with a lower risk of infection were more frequent in this group." (PMID 29940023, 2018). "The MD2 gene Ly96 was expressed prior to infection in the endothelium, stroma, and monocytes/macrophages." (PMID 36092940, 2022). "At 24 h after infection, the following genes were upregulated in infected macrophages transfected with the let-7e inhibitor compared to macrophages transfected with NC: Tlr7, Ly96/MD-2, Casp8, Map3k1, Mapk8, Ptgs2/Cox2, Csf 3/GCSF, and the ubiquitin-conjugating enzyme E2N (Ube2n)." (PMID 30555476, 2018). "We identified important genes DE in both our in vitro and in vivo infection models consistent with previous studies, namely, TLR3, IFIH1 (MDA5), SOCS1, OASL, DDX60, STAT1, MX1, CMPK2, LY96 (MD-2), STAT1, STAT2, TRIM25, IRF7, and IFIT5." (PMID 38675946, 2024). "It is interesting to note that several of these genes (IFIT5, LY96, RNF213 and EPST1) were previously identified in a study examining LPAI and HPAI infection in ducks and chickens." (PMID 35327988, 2022). "At the beginning of the infection (1 h), despite the increase in TLR4 expression, there was a decrease in the expression of CD14 and LY96 (also known as MD-2), which are important for lipopolysaccharide recognition." (PMID 36296238, 2022). "We identified 6 hub genes (IL1R1, CD163, TLR5, LY96, MMP9, and IRAK3) and 4 target miRNAs (miR-34a-5p, miR-103-3p, miR-107, and miR-124-3p) that affect the pathophysiological processes of T2DM and CS through ion transport, immune response, and infection." (PMID 40922361, 2025). "We observed that the gene expression of S100A9 and LY96 was increased in all patients, independent of infection days." (PMID 38262689, 2024).